EZH2 (enhancer of zeste 2 polycomb repressive complex 2 subunit)
Diseases named in the same sentence as EZH2 in open-access papers (continued):
Sharing a sentence is not in itself a finding about the gene and the disease.
lymphoma (continued). "Some anticancer drugs targeting mutant or wild‐type EZH2, such as GSK126, were used to inhibit EZH2‐mutant lymphoma cells, and EPZ‐6438 in a phase I/II clinical trial was designed for treating patients with relapsed or refractory B‐cell non‐Hodgkin lymphoma or advanced solid tumors." (PMID 37143582, 2023). "The detrimental effect of CRISPR-Cas9-mediated knockout of MEN1 on the proliferation of EZH2 mutant lymphoma lines KARPAS422 and SuDHL4 was also evident in competitive proliferation assays, and in xenograft experiments where depletion of MEN1 decreased the incidence of tumor formation." (PMID 37460547, 2023). "Therefore, SNHG17 regulates the proliferation, apoptosis, and drug sensitivity of lymphoma cells by interacting with miR-34a-5p/EZH2." (PMID 37988356, 2023). "In addition, overexpression of miR-34a-5p decreased EZH2 expression, whereas EZH2 was highly expressed in lymphoma cells (Fig 6CI and 6CIIs)." (PMID 37988356, 2023). "Dysregulation of the GC response by constitutively active EZH2 promotes lymphoma formation." (PMID 37626362, 2023). "As EZH2 is also overexpressed in T-cell leukemia and lymphomas, its inhibition is of interest in these entities and the effective but limited reduction in cell viability as single therapy was proven repeatedly but could not be validated in the current study." (PMID 37297005, 2023). "To understand whether miR-34a-5p affects the EZH2 pathway, we detected EZH2 protein expression after miR-34a-5p overexpression in lymphoma cells by western blotting (Fig 6DI and 6DII)." (PMID 37988356, 2023). "The association of EZH2 with the PRAME promoter and the transcriptional repression of PRAME in EZH2-mut lymphomas prompted us to explore whether EZH2-targeted therapy might induce PRAME and reactivate antitumor immunity in vivo." (PMID 35380993, 2022). "Particularly, c-Myc suppressed miR-29s transcription through a co-repressor complex with histone deacetylase 3 (HDAC3) and Enhancer of zeste homolog 2 (EZH2); and combined inhibition of HDAC3 and EZH2 restored miR-29s expression levels, which, in turn, caused lymphoma growth suppression." (PMID 36140219, 2022). "EZH2 inhibition induces PRAME expression and immune infiltrates in Ezh2-mutant lymphomas in vivo." (PMID 35380993, 2022). "The relevance of EZH2 is highly reported in several lymphomas." (PMID 35326620, 2022). "Epigenetic dysfunction, such as gain-of-function mutations of EZH2 and loss-of-function mutations of CREBP and EP300, disrupts the normal biological link between lymphoma cells and immune TME, and motivates immune evasion in GCB lymphoma." (PMID 35935878, 2022). "It has been shown that the combination of EZH2 inhibitors and immunotherapy may be effective in tumor therapy such as EZH2 mutant lymphoma." (PMID 36532284, 2022). "Differentiation after EZH2 inhibition has been reported in lymphoma." (PMID 35169119, 2022). "Interestingly, while tazemetostat shows the highest clinical efficacy in EZH2-mutant disease, it also provides some benefit in a subset of EZH2-WT lymphomas." (PMID 35426374, 2022). "Besides, EZH2 inhibitor can restore CD58 expression on the surface of lymphoma cells, which in turn increases IFN-γ secretion of T/NK cells against lymphoma cells." (PMID 34168659, 2021). "Both gain- and loss-of-function mutations in EZH2 have often been found in myeloid leukemias and lymphomas but are not common in solid tumors." (PMID 34900699, 2021). "In this study, we present a novel highly selective EZH2 inhibitor SHR2554, which specifically inhibits both wild-type and mutant EZH2 methyltransferase activity with similar potencies and is currently undergoing clinical trials for the treatment of lymphoma patients (NCT03603951)." (PMID 34503063, 2021). "However, a recent clinical study of the EZH2 inhibitor GSK2816126 on lymphomas, solid tumors and multiple myelomas showed little effect in treatment efficiency and was terminated." (PMID 33803458, 2021).
lymphoma (continued). "The EZH2 inhibitor Tazemetostat, is currently under clinical trial in lymphomas and other tumors." (PMID 33803458, 2021). "Similarly, EZH2 inhibition has been shown to reduce tumor burden and tumor growth in several preclinical models, such as lung cancer and lymphoma mouse models." (PMID 34638497, 2021). "However, some lymphomas are resistant to EZH2i, and EZH2i treatment alone is ineffective in case of EZH2-overexpressing solid tumors." (PMID 33761979, 2021). "Although the lack of efficacy precluded this combination from further study, the responses in patients with EZH2-mutant lymphomas suggests that a precision-medicine approach targeting this specific patient population may be effective." (PMID 35071240, 2021). "Conditional knock-out alleles have been successfully employed to study the in vivo role of many lymphoma-associated tumor suppressor genes encoding for transcription factors (BLIMP1), epigenetic modifiers (EZH2, CREBBP, KMT2D, TET2), small G proteins (GNA13) and ubiquitin ligases (FBXO11)." (PMID 34456919, 2021). "EZH2 is an attractive target for anti-cancer therapy because it is upregulated in multiple cancers, including, but not limited to, breast, prostate, melanoma, bladder cancer, and lymphoma." (PMID 33291558, 2020). "This suggests that mutations affecting this binding site promote that EZH2 is no longer regulated by miR-144 in lymphoma cells." (PMID 33233721, 2020). "EZH2 (enhancer of zeste) homolog is becoming a potential target for treating lymphoma." (PMID 35582230, 2020). "At the biennial meeting of the International Conference on Malignant Lymphoma (ICML) in Lugano, Switzerland (2017): Phase II Tazemetostat Trial (EPZ-6438) demonstrated an objective response rate of 29% in DLBCL with EZH2 mutation and 15% in DLBCL with wild-type EZH2." (PMID 33216822, 2020). "Due to its oncogenic role, the targeting of EZH2 might be a promising approach for lymphoma therapy." (PMID 32408898, 2020). "In c-MYC-induced lymphoma cell lines, downregulation of miR-26a has been reported to come along with cMYC-induced EZH2 expression, a histone methyltransferase member of the Polycomb-group (PcG) family of epigenetic gene silencers implicated in neoplastic development." (PMID 33362864, 2020). "FOXM1, Plk-1, and EZH2 are all described as interesting therapeutic targets in both DLBCL and MCL, and high expression of these genes is reported to be associated with poor survival in lymphoma patients." (PMID 31740676, 2019). "We show that DZNep inhibits proliferation and induces apoptosis of these cell lines independent of the type of lymphoma, the EZH2 mutation status and the MYC, BCL2 and BCL6 rearrangement status." (PMID 31419226, 2019). "Moreover, H3K27me2 has been suggested to perform repressive functions at intergenic sites that are likely altered in EZH2 mutant lymphoma cells." (PMID 31123059, 2019). "Hence, inhibiting EZH2 can be a successful strategy for treatment of lymphoma with EZH2 alterations." (PMID 31419226, 2019). "Moreover, BCL6 and the BCOR-PRC1 complex containing FBXL10 are necessary for EZH2-driven GC formation and lymphoma precursor lesions." (PMID 29352142, 2018). "Similarly, the small molecule inhibitor Astemizole can also inhibit EZH2/EED interaction which destabilizes PRC2 complex thereby decreasing the proliferation of lymphoma cells." (PMID 29556394, 2018). "Functional analysis has demonstrated that this mutation mediates gain-of-function of EZH2 enzymatic activity leading to increased levels of H3K27me3 and resulting in suppression of gene expression (e.g. TCF4, FOXP1, TCL1A, BIK, RASSF6P, CDKN1A) in lymphomas." (PMID 29556394, 2018). "Moreover, EPZ005687 can also inhibit H3K27 methylation induced by two EZH2 mutants (Y641 and A677), thereby killing lymphoma cells carrying the Y641 or A677 EZH2 mutant." (PMID 30510924, 2018).
lymphoma (continued). "Together, these data demonstrate that the pharmacological inhibition of EZH2 activity may provide a promising treatment for lymphomas and solid tumors bearing exaggerated EZH2 methyltransferase activity." (PMID 28758948, 2017). "Finally, it is important to note that the mechanism by which EZH2 controls GC B cell proliferation through regulation of CDKN1A is also relevant to the malignant lymphomas that arise from GC B cells." (PMID 29026085, 2017). "Many lymphoma cases showed high expression of EZH2, SUZ12, H3K27me3, and BMI1 in the tumor nuclei." (PMID 28412742, 2017). "Our current data indicate that this CDKN1A repression dependence of lymphoma cells is inherited from and based on the natural physiological function of EZH2 in GC B cells and is not an artifact of EZH2 somatic mutation or the malignant phenotype." (PMID 29026085, 2017). "How a decrease in H3K27me2 level contributes to the biology of EZH2-mutated lymphoma cells is not known." (PMID 26497210, 2016). "EZH2 deregulation interferes with the finely regulated balance between germinal center B cell proliferation and differentiation, blocking them in a proliferative and immature state, which constitutes a key determinant in lymphoma development." (PMID 26497210, 2016). "EZH2 gain-of-function mutations are not sufficient on their own for lymphoma development; however, they represent a driving hit in lymphoid transformation, in association with the deregulation of other genes, such as c-MYC or BCL2." (PMID 26497210, 2016). "Similarly, EPZ0056687 has been shown to induce apoptotic cell killing in heterozygous mutant EZH2 Y641 or alanine 677 lymphoma cells, with minimal effects on wild-type cell proliferation." (PMID 27329599, 2016). "Because EZH2 CN loss (located in 7q36.1) is common in MDS, EZH2 overexpression may be rare in high-grade patients, while solid cancers and lymphoma are rarely associated with genomic lesions of EZH2." (PMID 26812882, 2016). "Similarly, Astemizole is a small molecule inhibitor of EZH2/EED interaction which destabilizes PRC2 complex decreasing the proliferation of lymphoma cells." (PMID 27793053, 2016). "Compound 15 was found to have strong anti-proliferative activities (EC50 = 28–861 nM) against diffuse large B-cell lymphoma cells containing an EZH2 activating mutation, while lymphoma cells without an EZH2 mutation are generally insensitive." (PMID 27316347, 2016). "For example, EZH2 knockdown enhanced HOXA gene cluster expression in lymphoma cells." (PMID 26812882, 2016). "Additionally, somatic heterozygous mutations were first identified within the catalytic SET domain of EZH2 in lymphoma." (PMID 26304929, 2015). "Indeed, the DB lymphoma cell line which has an EZH2 mutation (Y646N, according to the COSMIC database) was observed to be particularly sensitive to the EZH2 inhibitor GSK343." (PMID 26300989, 2015). "Previously, EZH2 was reported to interact with HDAC3 to repress miR-29 in lymphomas." (PMID 25644061, 2015). "Finally, preclinical studies have shown that single agent EZH2 inhibitors induce significant cell killing only in EZH2 mutant-bearing lymphomas, which represent a fraction (20%) of GCB DLBCL patients with high unmet clinical need." (PMID 25493630, 2014). "Finally, tumor growth inhibition was assessed in 3 different EZH2 mutant lymphoma xenograft models (materials and methods section 6)." (PMID 25493630, 2014). "Indeed, EZH2 mutant lymphoma cell lines are insensitive to GRag treatment, while concentration-dependent cell killing is observed in EZH2 wild-type cells." (PMID 25493630, 2014). "We next investigated if the combination effect of EPZ-6438+CHOP could render EZH2 wild-type GCB lymphoma cell lines sensitive to EPZ-6438 (materials and methods section 1 and 2)." (PMID 25493630, 2014).
lymphoma (continued). "Mice with a B cell-specific loss of EZH2 or treated with an EZH2 inhibitor completely failed to form germinal centres, whereas mice engineered to express the lymphoma-associated EZH2Y641F mutant exhibited massive germ cell hyperplasia." (PMID 24678345, 2014). "In addition, another mutation within the EZH2 SET domain, A677G, has also been identified in Lymphomas and shown to have increased trimethylation efficiency." (PMID 24367611, 2013). "The fact that EZH2 is altered by overexpression/increased activity in epithelial cancers and lymphomas, yet inactivated in myeloid malignancy, argues that the biologic consequences of alterations in H3K27me3 may be tissue specific." (PMID 21811504, 2012). "EZH2 is a reported target of miR-26a in muscle and lymphoma cells, and of miR-26b in HeLa cells." (PMID 21941025, 2011). "Interestingly, the 3′UTR of EZH2 contains target sites for miR-26a and miR-26b, and EZH2 was shown to be targeted for repression by miR-26a in muscle and lymphoma cells, and of miR-26b in HeLa cells." (PMID 21941025, 2011). "Our work may be helpful in the selection of lymphoma patients for future trials of pharmacologic agents targeting EZH2 and EZH2-regulated pathways." (PMID 22194861, 2011). "In addition, miR-26a was also reported to negatively regulate Ezh2 expression in myoblasts and lymphoma cells." (PMID 20478051, 2010). "Thus, suppression of H1 expression by mutant EZH2 may benefit lymphoma cells and lead to a more aggressive phenotype." (PMID 40504770, 2025). "In cells with Enhancer of zeste homolog 2 (EZH2) gain-of-function mutations, combinatorial inhibition of MEN1 using MI-503 or VTP50469 with EZH2 inhibitor Tazemetostat (EPZ-6438) has been shown to decrease tumor burden and survivability in a lymphoma xenograft model." (PMID 38279330, 2024). "EZH2 has a well-defined oncogenic role in cancer initiation, progression, metastasis, metabolism, and drug resistance and in the modulation of anti-tumor immunity in cancers of the prostate, breast, bladder, and esophagus, as well as gastric and non-small-cell lung carcinoma and lymphomas." (PMID 38791289, 2024). "SNHG17 knockdown inhibited EZH2 expression, while miR-34a-5p overexpression weakened this trend, suggesting that the SNHG17/miR-34a-5p axis may affect the biological function of lymphoid cancer cells and tumor development by regulating the activity of the EZH2 signaling pathway." (PMID 37988356, 2023). "CREBBP, KMT2D, and EZH2 are thus frequent epigenetic hits, initially considered as direct tumor inducers regulating B-cell proliferation and differentiation, but now widely recognized for their additional role as modulators of lymphoma TME, in particular based on the data obtained in GEMM." (PMID 38022603, 2023). "Notably, the EZH2 CR mutant had a gain-of-function phenotype, giving significantly better rescue than that of WT EZH2 (P < 0.01) and phenotypically mimicking a gain-of-function mutant (EZH2 Y646F) that is well-studied in the human system and frequently found in lymphoma." (PMID 37733873, 2023). "Recurrent mutations of Tyr641 in EZH2 alter catalytic activity of PRC2 and induce increased levels of H3K27me3, which indicate that pharmacological inhibition of EZH2 activity may provide a novel therapeutic target for EZH2 mutant lymphoma." (PMID 34503063, 2021). "In both models, expression of the mutant Ezh2 knock-in allele did not lead to lymphomas; however, accelerated lymphomagenesis was observed when mice were crossed with VavP-Bcl2 transgenics or upon adoptive transfer of VavP-Bcl2 BM cells transduced with Ezh2Y641F vectors." (PMID 34456919, 2021). "In addition to controlling immune-related genes in lymphoma cells, EZH2 is critical for the maintenance of Treg identity after activation, suggesting that EZH2 inhibition may also be able to reduce the suppressive role of Tregs." (PMID 35071240, 2021).
lymphoma (continued). "Even though EZH2 has been pursued as a therapeutic target for several types of tumors, such as sarcoma, lymphoma, and malignant rhabdoid tumor (MRT), there is still much unknown how SMARCB1/INI1 drives EZH2 or how SMARCB1 interacts with the potential targets in pancreatic cancer." (PMID 34315468, 2021). "Indeed, MYC and EZH2 act in concert to silence tumor suppressor miRs in aggressive lymphoma cells." (PMID 32549409, 2020). "A number of PMTs are considered attractive therapeutic targets: EZH2, the catalytic subunit of the polycomb repressive complex 2 (PRC2), tri-methylates lysine 27 of histone 3 (H3K27), and oncogenic hyper-trimethylation of H3K27 is driven by overexpression or activating mutations of EZH2 in lymphoma." (PMID 31817960, 2019). "Even though effective when activating point mutations in the SET domain are driving lymphomas or in the background of tumours harbouring other epigenetic perturbations, targeting the catalytic activity of EZH2 has thus far failed to elicit the expected response in a number of other malignancies." (PMID 28678185, 2017). "Mechanistically, treatment with compound 15 reduced the cellular H3K27me3 levels and caused a broad range of transcriptional activation of EZH2/PRC2 target genes in sensitive lymphoma cells, while it did not significantly affect the gene expression patterns of insensitive cells." (PMID 27316347, 2016). "Interestingly, SUDLH8 is more sensitive to HKMTI-1-005 than the other lymphoma lines with WT EZH2, suggesting that increased sensitivity to this dual inhibitor will not be dependent on cancer cells carrying activating mutations but perhaps any mechanism of increased dependency on EZH2." (PMID 26300989, 2015). "Therefore, we expressed two lymphoma-specific EZH2 GOF mutants, A677G and A687V, in A375 cells." (PMID 25671303, 2015). "Hence SESN1-mediated mTOR pathway inhibition may be an important mechanism of reintroducing GRag sensitivity in EZH2 mutant lymphoma cells after EPZ-6438 treatment." (PMID 25493630, 2014). "First, we conducted a proliferation assay to compare the effects of the EZH2 inhibitor (iEZH2, Tazemetostat) and degrader (dEZH2, MS1943) on cell viability across various lymphoma cell lines." (PMID 40308579, 2025). "Currently, several strategies involving the combination of BCL6 inhibitors with several agents, including PRMT5 inhibitors, EZH2 inhibitors, STAT3 inhibitors and chemotherapy drug doxorubicin, have been explored for the treatment of lymphomas." (PMID 39815148, 2025). "The EZH2 inhibitor tazemetostat has been approved by the the United States Food and Drug Administration (US FDA) for treating certain lymphomas, demonstrating a 69% objective response rate in EZH2‐mutant patients during a phase II clinical trial." (PMID 40761481, 2025). "Cluster 1 (top right) included genes such as CD79A, PTPRC, EZH2, MMP9, IKBKB, or CASP8, which were upregulated in GCB lymphomas (top right colored in orange)." (PMID 41472741, 2025). "Selective inhibition of EZH2 by ZLD10A inhibits H3K27 methylation and is lethal in mutant lymphoma cells; therefore, it suppresses lymphoma cell proliferation." (PMID 37445833, 2023). "Our study aimed to address this discrepancy by evaluating the comparative efficacy of tazemetostat, an FDA-approved EZH2 inhibitor, and MS1943, an EZH2 degrader, across diverse lymphoma cell lines." (PMID 37760442, 2023). "Epigenetic alterations in lymphoma include those involved in DNA methylation (e.g. DNMT1), histone acetylation (e.g. CREBBP), histone methylation (e.g. EZH2) and non-coding RNA (e.g. miR-155)." (PMID 37869076, 2023). "GSK126, one of the first selective EZH2 inhibitors, was extensively tested in DLBCL lymphoma cell lines leading to significant growth inhibition and increased apoptotic rate with maximal potency after 2 days." (PMID 35715861, 2022).